RNF126 (ring finger protein 126)
Description:
E3 ubiquitin-protein ligase that mediates ubiquitination oF target proteins. Depending on the associated E2 ligase, mediates 'Lys-27'-, 'Lys-29'-, 'Lys-48'- and/or 'Lys-63'-linked polyubiquitination of substrates. Part of a BAG6-dependent quality control process ensuring that proteins of the secretory pathway that are mislocalized to the cytosol are degraded by the proteasome. Probably acts by providing the ubiquitin ligase activity associated with the BAG6 complex and be responsible for ubiquitination of the hydrophobic mislocalized proteins and their targeting to the proteasome. May also play a role in the endosomal recycling of IGF2R, the cation-independent mannose-6-phosphate receptor. May play a role in the endosomal sorting and degradation of several membrane receptors including EGFR, FLT3, MET and CXCR4, by mediating their ubiquitination. By ubiquitinating CDKN1A/p21 and targeting it for degradation, may also promote cell proliferation. May monoubiquitinate AICDA. Acts as a regulator of DNA repair by mediating 'Lys-27'- and 'Lys-29'-linked polyubiquitination of MRE11, thereby promoting the exonuclease activity of MRE11.
Synonyms: FLJ20552
Tractability: PROTAC: UniProt records ubiquitination sites on it; ubiquitination databases record sites on it; its protein half-life has been measured.
Gene: Protein-coding gene on chromosome 19 (647,526 to 663,233, reverse strand). Ensembl gene ENSG00000070423.
Subcellular location: Cytoplasm; Nucleus
Subcellular location (Human Protein Atlas): Nucleoplasm; Cytosol
Pathways (Reactome):
Immune System: Antigen processing: Ubiquitination & Proteasome degradation
Gene Ontology:
Molecular function: protein binding; ubiquitin protein ligase activity; epidermal growth factor receptor binding
Biological process: cytoplasm protein quality control by the ubiquitin-proteasome system; negative regulation of epidermal growth factor receptor signaling pathway; positive regulation of double-strand break repair via homologous recombination; proteasome-mediated ubiquitin-dependent protein catabolic process; protein K27-linked ubiquitination; protein K29-linked ubiquitination; protein monoubiquitination; regulation of cell population proliferation; retrograde transport, endosome to Golgi; ubiquitin-dependent protein catabolic process; ubiquitin-dependent protein catabolic process via the multivesicular body sorting pathway; protein K48-linked ubiquitination; protein K63-linked ubiquitination; protein polyubiquitination; protein ubiquitination
Cellular component: cytoplasm; nucleus; cytosol
Genetic constraint (gnomAD): Loss-of-function variants: 16 observed, 22.63 expected, observed/expected ratio (o/e) 0.71, 90% interval 0.48 to 1.07. The synonymous counts are far from expectation, so gnomAD's model fits this gene poorly and the ratio says little. Missense variants: 385 observed, 328.88 expected, observed/expected ratio (o/e) 1.17, 90% interval 1.08 to 1.27. Synonymous variants: 215 observed, 151.44 expected, observed/expected ratio (o/e) 1.42, 90% interval 1.27 to 1.59.
Homologues: Orthologues: chimpanzee RNF126 (100% identical), mouse Rnf126 (94% identical), guinea pig RNF126 (93% identical), macaque RNF126 (90% identical), rat Rnf126 (81% identical), pig RNF126 (81% identical), zebrafish rnf126 (72% identical), tropical clawed frog rnf126 (69% identical), dog RNF126 (59% identical). Paralogues in human: RNF115 (44% identical), RNF181 (16% identical).
Diseases named in the same sentence as RNF126 in open-access papers:
RNF126 is named in the same sentence as 33 diseases in open-access papers, as found by Europe PMC text mining. Sharing a sentence is not in itself a finding about the gene and the disease. The quoted sentences say what the papers report.
breast carcinoma (13 papers, 2016 to 2025). "For example, RNF126 is linked to early breast cancer metastasis and promotes breast cancer cell proliferation and development." (PMID 37620897, 2023). "Elevated expression of RNF126 has been reported as a prognostic biomarker in breast cancer, a cancer type associated with MEN1 gene mutations." (PMID 35941657, 2022). "The study demonstrated that breast cancer cells expressing elevated levels of RNF126 exhibited heightened replication stress and increased sensitivity to CHEK1 inhibitors, providing further insights into the intricate associations between CHEK1, RNF126, and breast cancer outcomes." (PMID 39473450, 2024). "Thus, high RNF126 expression appears to be associated with breast cancer metastasis and is enriched in cell cycle pathways." (PMID 36539893, 2022). "The dataset showed that RNF126 is associated with breast cancer metastasis." (PMID 36539893, 2022). "The observed menin–RNF126 interaction motivates further research as RNF126 inhibition could stabilize menin mutant proteins to (partially) rescue functions in MEN1 mutated breast cancer." (PMID 35941657, 2022). "A high level of expression of RNF126 in early breast cancer patients without lymph node metastases may indicate a high-risk type of metastatic disease, possibly due to RNF126, which may increase breast cancer cell proliferation and invasion." (PMID 36539893, 2022). "A similar discrepancy between transient and stable knockdown/knockout of RNF126 on cell proliferation has been reported in breast cancer." (PMID 41465608, 2025). "Among these, p21 and PDK1 are related to cancer cell proliferation and colony formation ability in breast cancer and are regulated via proteasomal degradation by RNF126." (PMID 41465608, 2025). "Treatment with ATR inhibitors increased cell death by triggering abnormal origin firing in breast cancer cells with higher RNF126 expression." (PMID 36539893, 2022). "Our results provide a proof-of-concept in preclinical models of a new paradigm for treating breast cancer with high expression of RNF126 via ATR inhibitors alone." (PMID 36539893, 2022). "Breast cancer cells with higher RNF126 expression have CDK2-mediated replication stress, which makes them potential targets for ATR inhibitors." (PMID 36539893, 2022). "In our model, we determined that breast cancer cells with a higher level of RNF126 are more sensitive to ATR inhibitors than breast cancer cells with a lower level of RNF126." (PMID 36539893, 2022). "ATR inhibitors were more effective at killing breast cancer cells with intact RNF126 due to replication stress compared with the corresponding cells with RNF126 knockdown." (PMID 36539893, 2022). "Cyclin-dependent kinase 2 (CDK2) was involved in regulating replication stress in breast cancer cells with intact RNF126." (PMID 36539893, 2022). "RNF126-expressing breast cancer cells exhibit CDK2-mediated replication stress that makes them potential targets for ATR inhibitors." (PMID 36539893, 2022). "Numerous E3 ubiquitin ligases, such as cIAP2, FBW7, RNF126, and HUWE1, have been documented to be associated with breast cancer tumorigenesis and drug resistance." (PMID 34650035, 2021). "RNF126 protein is also highly expressed in invasive breast cancer tissues where it targets p21 for degradation, thus promoting breast cancer cell proliferation." (PMID 32131492, 2020). "One study has indicated that depletion of RNF126 in breast cancer cells can suppress colony formation and tumorigenicity in mice." (PMID 32131492, 2020). "RNF126 protein is also highly expressed in the invasive breast cancer tissue, where it targets p21 for ubiquitination and subsequent proteasome-mediated degradation, promoting breast cancer cell proliferation." (PMID 30529286, 2018).
breast carcinoma (continued). "Here we depleted RNF126 expression in human MDA-MB-231 breast carcinoma cells and human A549 lung carcinoma cells using two shRNA sequences (shRNF126 #1 and 2), with an shRNA against luciferase mRNA (shLuc) serving as a control." (PMID 27462466, 2016). "Most breast cancer cell lines expressed RNF126 at higher levels than did mammary epithelial MCF-10 A cells." (PMID 27462466, 2016). "Under this scenario, it may seem counter-productive to inhibit RNF126, as BRCA1 deficiency is one of the notable markers in breast cancer." (PMID 37760968, 2023). "Taken together, these data suggest a mechanism of action in which inhibition of ATR in intact RNF126 cells induces an increase in CDK2-mediated replication stress in breast cancer cells, ultimately leading to DNA damage, replication fork collapse, cell apoptosis, and cell death." (PMID 36539893, 2022). "CDK2 may mediate the killing effect of ATR inhibitors on RNF126 high-expression breast cancer cells." (PMID 36539893, 2022). "Interestingly, although we have previously reported that RNF126 knockdown reduces CHEK1 expression, we did not observe a synergistic lethal effect of ATR inhibitors on breast cancer cells with knockdown of RNF126." (PMID 36539893, 2022). "We hypothesized that the lower efficiency of ATR inhibitors in breast cancer cells with RNF126 knockdown might be explained by the relative reduction in replication stress." (PMID 36539893, 2022). "However, the replication process of breast cancer cells with RNF126 knockdown was only mildly affected, with only mild changes in the replication elongation rate and new replication initiation rate." (PMID 36539893, 2022). "RNF126 promoted breast cancer cell proliferation, growth, migration, and invasion." (PMID 36539893, 2022). "Thus, we presumed that CDKs induce endogenous replication stress in breast cancer cells with RNF126." (PMID 36539893, 2022). "Interestingly, our results showed that breast cancer cells with RNF126 knockdown were less sensitive to ATR inhibitors than the cells with intact RNF126." (PMID 36539893, 2022). "Given the lack of normal paired tissues in GSE11121 dataset, we analyzed the expression of RNF126 in 44 early-stage (T1–T3, N0, M0) breast cancer patients in TCGA to ascertain whether RNF126 was higher expression in tumor tissues." (PMID 36539893, 2022). "To determine whether CDKs mediate endogenous replication stress in breast cancer cells with intact RNF126, we next measured the viability of breast cancer cells with or without RNF126 after co-treatment with AZD6738 and NU2058, a CDKs inhibitor." (PMID 36539893, 2022). "Thus, we conclude that RNF126 promotes breast cancer cell proliferation, cell growth, migration, and invasion." (PMID 36539893, 2022). "After using CDKs inhibitors to pretreat breast cancer cells with a higher level of RNF126, we observed that the cell-killing effect of ATR inhibitors could be counteracted by the inhibitors, in conjunction with an alleviates replication stress." (PMID 36539893, 2022). "We demonstrated that breast cancer cells with higher RNF126 expression could stall the replication fork and trigger abnormal replication initiation after ATR inhibitor application." (PMID 36539893, 2022). "Regardless, these results still suggested that RNF126 might be a potential therapeutic biomarker for breast cancer, even though the relationship between RNF126 protein expression and metastasis was still unclear." (PMID 36539893, 2022). "We postulated that RNF126 may activate the cell cycle pathway and thereby promoted thereby promote breast cancer's malignant evolution." (PMID 36539893, 2022). "In brief, our results suggest that higher expression of RNF126 may accelerate breast cancer metastasis and that RNF126 may be an effective biological target for ATR inhibitors." (PMID 36539893, 2022).
breast carcinoma (continued). "High expression of RNF126 is an independent predictor of a poor prognosis in invasive breast cancer and is considered a potential biomarker for cancer responsiveness to checkpoint kinase 1 (CHK1) inhibitors, as RNF126 increases gene expression of CHK1 in breast cancer cells." (PMID 30529286, 2018). "Thus, CDK2-mediated replication stress in breast cancer with a high level of RNF126 expression might be one of the reasons for the sensitivity of these breast cancer cells to ATR inhibitors." (PMID 36539893, 2022). "This study explores the relationship between the E3 ubiquitin ligase Ring finger protein 126 (RNF126) and early breast cancer metastasis and tests the hypothesis that RNF126 determines the efficacy of inhibitors targeting Ataxia telangiectasia mutated and Rad3-related kinase (ATR)." (PMID 36539893, 2022). "Thus, we hypothesized that breast cancer cells with RNF126 knockdown could be more sensitive to ATR inhibitors." (PMID 36539893, 2022). "As expected, HER2 KD or lapatinib, a HER2 inhibitor, decreased the RNF126 mRNA and protein levels in the HER2‐positive breast cancer cell line BT474." (PMID 36563124, 2023). "Targeting RNF126 in TNBC and improving ATR inhibitor sensitivity in breast cancer has been experimentally demonstrated, thereby potentiating its efficacy." (PMID 37760968, 2023). "RNF126 promotes cell proliferation in a variety of cancer cells, but the biological function of RNF126 in promoting breast cancer metastasis in early breast cancer is lacking." (PMID 36539893, 2022). "Nonetheless, our results showed that RNF126-depleted breast cancer cells were not sensitive to CHEK1 and ATR inhibitors." (PMID 36539893, 2022). "In conclusion, our model demonstrates that the high expression of RNF126 in early breast cancer patients without lymph node metastasis indicates a high-risk type of metastasis." (PMID 36539893, 2022). "However, we found that AKT pathway inhibitors exhibited dominant inhibition of RNF126 expression in several breast cancer cell lines (data not shown)." (PMID 36563124, 2023). "However, the proliferation regulatory ability of RNF126 in breast cancer metastasis has not yet been evaluated." (PMID 36539893, 2022). "Furthermore, analysis of 44 cases of early breast cancer patients without lymph node metastasis in TCGA found that RNF126 was highly expressed in tumor samples compared with normal breast tissues." (PMID 36539893, 2022). "A reanalysis of the GSE11121 dataset of early breast cancer patients without lymph node metastasis found that RNF126 could promote breast cancer metastasis, and we verified this result in vitro and in vivo experiments." (PMID 36539893, 2022). "RNF126 expression was not higher in HER2‐positive breast cancers than in other types of breast cancer and their expressions were not correlated in breast cancer." (PMID 36563124, 2023). "The results showed that RNF126 knockdown increased p-ATR expression, which meant that the function of ATR protein had been activated, but ATR inhibitors could not effectively kill breast cancer cells with RNF126 knockdown." (PMID 36539893, 2022). "The RNF126-related network modules were identified by WGCNA, whereas cell viability, invasion, and migration assays were performed to evaluate the biological characteristics of breast cancer cells with or without RNF126 knockdown." (PMID 36539893, 2022). "Finally, we explored ERK-mediated RNF126 and PDK expression in attached and detached cells using normal mammary epithelial MCF-10A cells, seven breast cancer cell lines including MDA-MB-231 cells and lung cancer A549 cells." (PMID 27462466, 2016).
bladder cancer (6 papers, 2021 to 2024). "RNF126 is highly expressed in various cancers and strongly associated with tumorigenesis, including bladder cancer." (PMID 37497216, 2023). "Depletion of RNF126 remarkably impaired proliferation and metastasis of bladder cancer cells via modulation of the EGFR/PI3K/AKT pathway." (PMID 37215134, 2023). "RNF126 expression was elevated in bladder cancer tissues via a TCGA database analysis." (PMID 37215134, 2023). "Inhibition of RNF126 oncoprotein could be a novel approach for bladder cancer therapy." (PMID 37215134, 2023). "RNF126, another member of the RNF protein family, has been found to promote the malignant properties of human bladder cancer cells by mediating the ubiquitination of the tumor suppressor protein phosphatase and tensin homolog." (PMID 37249301, 2023). "It has also been reported that RNF126 can directly bind and regulate PTEN stability through polyubiquitination, making RNF126 an attractive target for augmenting cisplatin-based chemotherapy and regulating bladder cancer tumorigenesis." (PMID 37497216, 2023). "For example, RNF126 could ubiquitinate PTEN and induce its proteasome degradation, thereby regulating the PI3K‐AKT signalling pathway to promote the cellular proliferation and migration of bladder cancer." (PMID 37132043, 2023).
invasive breast carcinoma (5 papers, 2018 to 2024). A carcinoma that infiltrates the breast parenchyma. "We have reported that RNF126 may be highly expressed in invasive breast cancer and that its expression is associated with a poor prognosis." (PMID 36539893, 2022). "High expression of RNF126 is an independent predictor of poor prognosis in invasive breast cancer and is considered a potential biomarker for cancer responsiveness to checkpoint kinase 1 (CHK1) inhibitors." (PMID 32131492, 2020).
tongue cancer (4 papers, 2016 to 2022). A malignant neoplasm affecting the tongue. "The previous study demonstrated that RNF126 promotes tongue cancer progression through PI3K/AKT signaling pathway." (PMID 33664240, 2021). "RNF126 promotes the proliferation and viability of tongue cancer by regulating the AKT signaling pathway." (PMID 29052520, 2017). "In order to find the tongue cancer‐related E3 ligases, we screened the human E3 ubiquitin ligase library and found the candidate molecule, RNF126." (PMID 27227488, 2016). "Then, we observed that the knockdown of RNF126 also inhibited the cell viability of tongue cancer cells." (PMID 27227488, 2016). "During the observation periods, the volume of subcutaneous tumor which originated from the stable RNF126‐knockdown tongue cancer cells was smaller than that from the control group." (PMID 27227488, 2016). "To determine the function of RNF126 in tongue cancer development, we focused on the downstream signaling pathway of EGFR." (PMID 27227488, 2016). "RNF126 can promote the cell proliferation of tongue cancer and gastric cancer cells." (PMID 36539893, 2022). "In this study, we contributed to determine the role of RNF126 in the development of tongue cancer." (PMID 27227488, 2016). "Further study is needed to determine whether RNF126 is a potential treatment target for tongue cancer." (PMID 27227488, 2016). "Firstly, we confirmed that RNF126 affected the proliferation of tongue cancer cells." (PMID 27227488, 2016). "In conclusion, our data clearly established the role of RNF126 in the oncogenesis of tongue cancer." (PMID 27227488, 2016). "The growth and viability of human tongue cancer cells were inhibited with the knockdown of RNF126." (PMID 27227488, 2016). "In order to find the oral cancer‐sensitive E3 ubiquitin ligases, we screened the human E3 ubiquitin ligase library and found that RING finger protein 126 (RNF126) might be the potential molecule involved in the occurrence of tongue cancer." (PMID 27227488, 2016). "In this study, we further analyzed the role of RNF126 in the oncogenesis of tongue cancer." (PMID 27227488, 2016). "This study aims to analyze the role of RNF126 in the oncogenesis of tongue cancer." (PMID 27227488, 2016).
ovarian carcinoma (3 papers, 2017 to 2025). A malignant neoplasm originating from the surface ovarian epithelium. "Moreover, approximately 1.5 to 3 times more cells were positive for EthD-III in RNF126-depleted ovarian cancer cells compared to control cells." (PMID 41465608, 2025). "Thus, we next explored whether RNF126 depletion affects the peritoneal colonization of ovarian cancer." (PMID 41465608, 2025). "RNF126 was found to positively regulate BRCA1 by directly interacting with E2F1 for homologous recombination in breast and ovarian cancer." (PMID 29052520, 2017). "In addition, RNF126 can promote homologous recombination by upregulating BRCA1 expression in breast and ovarian cancers." (PMID 32131492, 2020).
gastric cancer (2 papers, 2020 to 2022). A primary or metastatic malignant neoplasm involving the stomach. "Overexpression of RNF126 can promote proliferation in the tongue and gastric cancer cells." (PMID 36539893, 2022).